PDGFB (platelet derived growth factor subunit B)
Diseases named in the same sentence as PDGFB in open-access papers (continued):
Sharing a sentence is not in itself a finding about the gene and the disease.
glioma (continued). "An IL-8-dependent recruitment of MSCs was detected in glioma, and it has also been shown that platelet-derived growth factor subunit B (PDGFB), vascular endothelial growth factor (VEGF), and transforming growth factor beta-1 (TGF-β1) can induce MSC migration." (PMID 33117154, 2020). "RNAseq analysis also indicated regulation of several pathways related to HIF-1α and VEGF such as NF-kappaB, PDGFb and Ang/Tie2 signaling for RNAseq of brain microvessels from experimental stroke and glioma models." (PMID 32529267, 2020). "We first generated a dose-response curve in all 3 human glioblastoma cell lines and in PDGFB-induced glioma primary cultures (PIGPCs) derived from the glioma mouse model." (PMID 33142235, 2020). "To recapitulate the genetic events and subsequent molecular evolution of the disease, we used the RCAS-PDGF-B/Nestin-Tv-a; Ink4a/Arf−/−; Pten−/− transgenic mouse model of PDGFβ-driven glioma (PDG mice)." (PMID 31481662, 2019). "In this glioma model, most PDGFB-transduced mice develop gliomas within 12 weeks of age; these lesions present either oligodendroglial or glioblastoma-like morphology." (PMID 29391393, 2018). "Lrig1 was expressed in PDGFB-induced gliomas in wild-type mice as assessed using in situ hybridization." (PMID 29391393, 2018). "In summary, Lrig1 is a haploinsufficient suppressor of PDGFB-driven glioma, possibly in part via negative regulation of MET-driven cell migration and invasion." (PMID 29391393, 2018). "In the present study, we investigated the role of physiological Lrig1 expression in PDGFB-induced glioma in mice and analyzed the effects of forced LRIG1 overexpression on human glioblastoma xenografts in vivo and on human glioblastoma cells in vitro." (PMID 29391393, 2018). "A recent study in a murine model of PDGFB-driven gliomas (resembling a proneural type GBM) showed that osteopontin secreted by tumour-associated astrocytes, via CD44 signalling promotes stem cell properties and glioma resistance to radiation." (PMID 28030801, 2017). "In murine PDGFB-induced glioma cultures and primary human GBM cultures stroma-derived osteopontin was responsible for up-regulation of NANOG, SOX2, OCT4, and ID1 expression." (PMID 28030801, 2017). "Transcriptomic data showed that Spp1 was up-regulated specifically in glioma-associated astrocytes compared to normal astrocytes in murine PDGFB-driven gliomas and proneural human GBMs." (PMID 28030801, 2017). "Retroviruses carrying v-sis (PDGFB) injected into normal mice have yielded astrocytic tumors, with varying glioma types generated when injected in Cdkn2a-null mice." (PMID 29052807, 2017). "This is a genetically-engineered murine model of PDGFB-driven gliomas in which the low-grade phenotype is predominant." (PMID 27074575, 2017). "Expression of BIRC3 in a PDGFB-dependent murine model of glioma resulted in shorter-symptom free survival compared to controls and also resulted in a shift to a more malignant glioma phenotype." (PMID 27074575, 2017). "Together, these data suggest that monocytes and macrophages can drive elements of a stem cell phenotype in PDGFB-induced gliomas via IL1β expression." (PMID 25987130, 2015). "To study the functional role of CX3CR1/CX3CL1 signaling in GBM, we used a genetically engineered mouse model (GEMM) of adult PDGFB-driven gliomas, which is based on RCAS/Tv-a, a somatic cell-specific gene transfer system." (PMID 25987130, 2015). "In any case, the results herein presented, showing that Lrig2 promoted PDGFB-induced glioma in mice, are consistent with the previous finding that LRIG2 expression predicts poor survival in human oligodendroglioma patients." (PMID 24023893, 2013).
glioma (continued). "The phenotype of Lrig2E12-/- mice showed that Lrig2 was a promoter of PDGFB-induced glioma, and Lrig2 appeared to have important molecular and developmental functions that were distinct from those of Lrig1 and Lrig3." (PMID 24023893, 2013). "Because the gliomas in our animal model were induced by PDGFB, we find it likely that the tumor promoting effect of Lrig2 was mediated by regulation of PDGF signaling." (PMID 24023893, 2013). "The PDGFB-induced gliomas are generated by an autocrine/paracrine stimulation and expansion of PDGFR-α positive glial progenitor/neural stem cells present in the newborn mouse brain." (PMID 22931209, 2012). "We went on investigating brain tumors and showed that miR-21 is overexpressed in glioma tissue and primary cultures established from RCAS/PDGFB-induced mouse gliomas, mimicking human high grade gliomas." (PMID 22931209, 2012). "We also investigated the effect on miR-21 expression in glioma-derived cancer initiating cells (GICs) cultured as spheres derived from PDGFB-induced tumors in neonatal Gtv-a mice." (PMID 22931209, 2012). "The expression of miR-21 in PDGFB-induced mouse glioma was confined to the tumor areas as shown by in situ hybridization." (PMID 22931209, 2012). "Here we show that in murine gliomas induced by human PDGFb (hPDGFb), glioma progression can occur by expansion of the recruited cells, and that these cells unrelated to glioma cell-of-origin can be corrupted to become bona fide tumor." (PMID 21754979, 2011). "Using the RCAS/TV-A system we established mouse glioma cell lines, derived from PDGFB induced tumors, in Ntv-a (the avian TVA receptor for RCAS virus driven by Nestin promoter) transgenic mice with wild type, Ink4A-/- or Arf-/- genetic backgrounds." (PMID 21733196, 2011). "PDGFRA and PDGFA have been shown to be expressed in tumour cells, whereas PDGFB and PDGFRB have been found in glioma-associated endothelial cells." (PMID 19707201, 2009). "Our work shows that PDGFB and mutant IDH synergize to accelerate gliomagenesis in the absence of other mutations, suggesting that mutant IDH and high levels of PDGFB are sufficient to induce glioma." (PMID 40060572, 2025). "In human glioma samples, PDGFB ChIP-seq enrichment at these loci was lowest in a recurrent mtIDH tumor and was highest in a wtIDH tumor, which suggests that loss of centromeric binding in mIDH tumors may contribute to disease progression." (PMID 40060572, 2025). "Finally, we identified the immune compartment as the predominant source of PDGFB in mIDH glioma, confirming that immune-derived PDGFB can translocate to the nucleus of glioma cells and bind chromatin." (PMID 40060572, 2025). "We used a genetically engineered mouse model of adult PDGFb-driven gliomas based on RCAS/Tv-a to implant primary RFP-labeled glioma cells into KO (n = 8) and respective WT control mice (n = 7), to determine the impact of host-derived GPNMB for glioma formation and growth." (PMID 38566120, 2024). "Moreover, glioma was detected in the brains of 3 out of 4 mice injected with RCAS-PDGFB + shGL2 and 4 out of 6 mice injected with RCAS- PDGFB + shCsmd1 although the mice did not exhibit any glioma symptoms." (PMID 38561856, 2024). "On the other hand, TAMs signal the glioma cells through the PDGFB to PDGF receptor alpha (PDGFRα) axis, which could trigger downstream phosphatidylinositol 3 kinase (PI3K) and mitogen-activated protein kinase (MAPK) pathways." (PMID 38515213, 2024). "Additionally, we observed reduced CSMD1 levels in mouse brain tumor models and glioma patients and Csmd1 knockdown promoted brain tumor development in a PDGFB-induced glioma mouse model and orthotopic xenograft model." (PMID 38561856, 2024). "Consequently, here, we aimed at using MRI and [18F]FET-PET to identify typical neuroimaging characteristics of the platelet-derived growth factor B (PDGFB)-driven glioma model using the RCAS-tva system." (PMID 36358353, 2022).
glioma (continued). "Genetic alterations, such as PDGFB amplification, the homozygous loss of Cyclin Dependent Kinase Inhibitor 2A (CDKN2A), and coding for p16INK4A and p14ARF, show high frequency in human glioma." (PMID 36358353, 2022). "Even more so, the discrimination of undiscovered potential drivers of gliomagenesis can be addressed by the establishment of a novel genetic forward screen using the retroviral integration capacity of the RCAS virus for detecting potential novel oncogenes in the PDGFB-driven glioma model." (PMID 36358353, 2022). "In a p16 Arf–/– PDGFB murine glioma model an endogenous ionotropic signaling has been identified within tumor cells, demonstrating that glioma cells not only respond to GABA, but they can also release it in the TME, limiting cell proliferation of both murine and patient-derived GBM cells." (PMID 34690699, 2021). "Moreover, STAT5B can drive tumour progression in a PDGFB-driven glioma model and this involves increased BCL2L1 expression." (PMID 33478100, 2021). "Moreover, analysis of PDGFB/shp53-induced murine gliomas revealed that both DLK1 and HIF-2a were strongly expressed and showed a significant co-localization only in the perivascular and perinecrotic niches." (PMID 33142235, 2020). "In addition, microarray analysis revealed that the PDGFB-driven glioma had a significant increase in other anti-inflammatory (M2) mediators, including IL1R2, IRF7, and STAT3." (PMID 33020472, 2020). "Furthermore, in RCAS/mCherry–PDGFB-induced gliomas, fluorescent YFP signal was visualized only in the YFP–IDH1, but not YFP–IDH1R132H, tumors despite a modest decrease of mCherry signal in the latter." (PMID 30416682, 2018). "Here, we investigated the role of Lrig1 in platelet-derived growth factor (PDGF)-induced experimental glioma in mice by introducing mono-allelic and bi-allelic deletions of Lrig1 followed by inducing gliomagenesis via intracranial retroviral transduction of PDGFB in neural progenitor cells." (PMID 29391393, 2018). "Likewise, in the RCAS/PDGFB glioma model, weak YFP staining was seen in YFP–IDH1R132H glioma cells in contrast to prevalent nuclear staining in YFP* glioma cells." (PMID 30416682, 2018). "Ectopic expression of PDGFB in Ntv-a mice induces gliomas of predominantly a low-grade phenotype." (PMID 27074575, 2017). "We generated primary cultures from PDGFB-driven gliomas generated in NiG mice." (PMID 25987130, 2015). "Incidence of PDGFB-induced glioma for the respective histological grade." (PMID 24023893, 2013). "Intriguingly, Lrig2E12-/- mice were protected against PDGFB-induced glioma." (PMID 24023893, 2013). "An elevated expression of miR-21 was found in PDGFB-induced mouse glioma." (PMID 22931209, 2012). "However, PDGFB overexpression or amplification is uncommon in pediatric gliomas and an analysis of PDGFB-driven brainstem glioma models demonstrated that they are characterized by a pro-angiogenic phenotype with increased expression of proneural genes more reflective of adult glioblastomas." (PMID 33768215, 2020). "Therefore, our current demonstration that the LRIG1 expression level is a determinant of the aggressiveness of PDGFB-driven gliomas may be highly relevant to the etiology of human gliomas." (PMID 29391393, 2018). "Since tyrosine phosphorylation is one of the first steps in growth factor receptor signaling activated in tumorigenesis, our findings raise possibilities that NFIX could be a substrate for some oncogenic growth factor such as PDGFB, with which it has been shown to cooperate in glioma formation." (PMID 19337383, 2009).
glioma (continued). "In mIDH glioma, high levels of IDH1R132H decrease nuclear localization of PDGFB, rendering PDGFB unable to bind centromeric heterochromatin, perhaps through changes to CENPB binding." (PMID 40060572, 2025). "Ubiquitous activation of mutant Ppm1d was modeled using the Meox2-Cre driver, and primary gliomas were modeled using the RCAS/tv-a system to introduce Cre and PDGFB co-drivers into Nestin-positive neural stem cells." (PMID 41394550, 2025). "In contrast, PDGFB, SDF-1α, and IL-8 exhibited patient-specific effects, suggesting variability in glioma subtype responsiveness." (PMID 40867240, 2025). "Microglia-derived PDGFB and SDF-1α significantly enhanced invadopodia activity in primary GBM cells, particularly in glioma subtypes expressing moderate levels of total Pyk2." (PMID 40867240, 2025). "In both HGG murine models (PDGFb and BRAF V600E), myeloid cells were the most abundant immune cell types in the TME, reflecting the immune landscape observed in glioma patients." (PMID 40527978, 2025). "Microglia-derived cytokines and chemokines, particularly PDGFB, EGF, SDF-1α, IL-6, and IL-8, activate Pyk2, but only PDGFB, EGF, SDF-1α and IL-6 promote Pyk2-related glioma cell invasion and proliferation." (PMID 40867240, 2025). "PDGFB, EGF, and SDF-1α all promoted glioma cell migration in a Pyk2-dependent manner, as their effects were abolished upon Pyk2 knockdown." (PMID 40867240, 2025). "In the RCAS- PDGFb and the GL261 (n = 3) murine glioma model, we observed comparable expressions patterns to our in vitro protein isolations." (PMID 38566120, 2024). "To test the effects of soluble DLK1 on glioma growth in vivo, we generated a mouse model for the overexpression of soluble DLK1 together with PDGFB using the RCAS/tv-a system." (PMID 33142235, 2020). "Consistently, we observed equivalent glioma penetrance between mice co-transduced with PDGFB and YFP* (100% or 8/8) and those co-transduced with PDGFB and YFP–IDH1R132H (88% or 7/8)." (PMID 30416682, 2018). "For example, retrovirally transduced expression of v-sis or PDGFB in GFAP-tva mice resulted in oligodendrogliomas or mixed oligoastrocytomas in 40% of the mice, with 60% of NES-tva mice developing similar gliomas." (PMID 29052807, 2017). "PDGFB cDNA was detected in all gliomas, and hPTN cDNA was present in all mice where RCAS-PDGFB and RCAS-PTN were combined." (PMID 27806344, 2016). "While examining human glioma scRNA-seq datasets, we found that expression of PDGFB was largely absent from tumor cells, which were frequently PDGFRA+ in mIDH tumors." (PMID 40060572, 2025). "We hypothesized that PDGFB and mutant IDH, which occur uniformly in mIDH glioma, may interact to promote glioma formation." (PMID 40060572, 2025). "Surprisingly, our immunoblotting analyses revealed that the mature form of PDGFB was largely absent from mouse cortex, PDGFBwt mouse glioma samples and human glioma samples." (PMID 40060572, 2025). "Congruently, pharmacological inhibition of CSF1R (BLZ945) in a PDGFB-driven GBM mouse model skewed macrophages to an immune-stimulating state blocking glioma progression and enhancing survival without depleting microglial cells." (PMID 38665919, 2024). "Our study provided a multilayered profiling of a PDGFB-driven glioma mouse model using the RCAS-tva delivery system and discovered radiological, histological, and metabolic features that are comparable to human high-grade glioma." (PMID 36358353, 2022).
glioma (continued). "It comprises genetic features of the proneuronal glioma subtype by combining PDGFB amplification with the lack of cell cycle regulator Cdkn2a." (PMID 36358353, 2022). "As EMT induction factor, transcription factors, the expression of SNAI1, SNAI2, TWIST1, and PDGFB was significantly higher in high-grade, elderly glioma patients, IDH-wildtype, 1p19q non-codel glioma patients." (PMID 32154177, 2020). "Given the overriding role of IDH1R132H against oncogenic PDGFB in anchorage-independent growth, we predicted that expression of IDH1R132H with PDGFB from the same transcript would prevent spontaneous glioma initiation and growth even in the glutamine-rich microenvironment." (PMID 30416682, 2018). "However, using G/tv-a wild type mice in which gliomas are induced by PDGFB in only roughly a third of the injected mice, we found that PTN markedly enhanced PDGFB-induced tumor formation." (PMID 27806344, 2016). "By employing the RCAS/tv-a mouse model, we provide evidence that PTN is not sufficient to induce glioma development, but augments PDGFB-induced gliomagenesis by increasing Akt activation in neural progenitor cells." (PMID 27806344, 2016). "For instance, EGF and PDGFB were clustered together and they are both involved in several pathways: cytokine-cytokine receptor interaction, MAPK signaling pathway, gap junction, focal adhesion, glioma and regulation of actin cytoskeleton." (PMID 21726470, 2011). "The observations that PDGFB is largely immune-derived, sufficient to generate glioma in the absence of mutations and synergizes with IDH1R132H to accelerate disease progression raise the possibility that exogenous PDGFB may contribute to gliomagenesis." (PMID 40060572, 2025). "To test this hypothesis, we utilized surgically-resected human glioma samples and developed a new immunocompetent in utero electroporation model of PDGFB-driven glioma to investigate a non-canonical role for PDGFB exists in the nucleus." (PMID 40060572, 2025). "Using the PDGFb-driven replication-competent avian sarcoma-leukosis virus/ tumor virus A (RCAS/Tv-a) murine high-grade glioma model injected into GPNMB-KO and control mice, we demonstrate that host-derived GPNMB is of detrimental importance for glioma growth and immune cell composition." (PMID 38566120, 2024). "In addition, neutralizing neutrophils by using a monoclonal antibody against Ly6G resulted in increased survival of an IDH1–wild-type (WT) glioma model, but not an IDH1-mutant (MUT) PDGFB-driven glioma mouse model." (PMID 36594465, 2023). "Finally, forced expression of DLK1 resulted in more invasive tumor growth in a PDGFB-induced glioma mouse model without affecting overall survival." (PMID 32205867, 2020). "In glioma, PDGFB and its cognate receptor, PDGFRA, are detected in mIDH tumors, whereas, in the non-tumor human brain, PDGFB is minimally expressed by microglia and vascular cells, and PDGFRA is highly expressed by OPCs." (PMID 40060572, 2025). "A PDGFB::LRP1 has not yet been reported in ependymomas or subependymomas, but only in one low-grade glioma without a definite histological diagnosis." (PMID 38581034, 2024). "In a glioma mouse model induced by human PDGFb, CD133 expressing cells were among recruited cells and were not derived from the progeny of glioma cell-of-origin." (PMID 23637986, 2013). "We observed that IDH1R132H was highly suppressive of subcutaneous tumor growth driven by platelet-derived growth factor B (PDGFB), but IDH1R132H tumor growth and glioma penetrance were virtually indistinguishable from those of IDH1-wildtype tumors in orthotopic models." (PMID 30416682, 2018).